ENSG00000285897 (novel transcript)
Gene: Protein-coding gene on chromosome 17 (58,345,206 to 58,417,595, reverse strand). Ensembl gene ENSG00000285897.
Genetic constraint (gnomAD): Missense variants: 760 observed, 992.8 expected, observed/expected ratio (o/e) 0.77, 90% interval 0.72 to 0.81. Synonymous variants: 342 observed, 383.35 expected, observed/expected ratio (o/e) 0.89, 90% interval 0.82 to 0.98.